CD4 (CD4 molecule)
Diseases named in the same sentence as CD4 in open-access papers (continued):
Sharing a sentence is not in itself a finding about the gene and the disease.
AIDS (continued). "The definition of “late diagno-sis” has been the subject of debate and controversy, though in Europe the term is taken to imply patients who at the time of diag-nosis present CD4+ lymphocyte counts of < 350 cells/mm3, or show clinical manifestations of AIDS." (PMID 22143719, 2012). "Among LP/AHD, the proportion of AIDS presenters has increased over time and the immunological status at presentation is severely compromised with a CD4+ count frequently <50 cells/μL." (PMID 22110905, 2012). "Estimates from fitting a univariate (unadjusted) and a multivariable (adjusted) linear mixed model on all repeated measurements of CD4 cell counts (square root transformed) taken from seroconversion to end of follow-up, cART initiation or clinical AIDS onset." (PMID 22412867, 2012). "The continuous killing of CD4+ T cells in the course of HIV-1 infection inevitably leads to an impaired immune response, the acquired immune deficiency syndrome (AIDS)." (PMID 23035819, 2012). "Recent HIV surveillance data suggest that approximately 33% of HIV-infected persons in the United States present for HIV testing late and have AIDS (CD4+ cell count <200 cells/mL or an AIDS-defining illness) within one year after HIV diagnosis." (PMID 21941640, 2012). "The promises of immune reconstitution and normal life expectancy, however, fall short for a number of patients, either through inadequate recovery of CD4+ T-cell counts or the occurrence of non-AIDS defining malignancies." (PMID 22203858, 2012). "Arevalo’s patient had AIDS and a CD4 count of 3 cells/mm3; a focal area of sclerosed retinal vessels was noted after intraocular injections of vancomycin and gentamicin for presumed endophthalmitis." (PMID 22311604, 2012). "In the pre and early cART eras, costing studies attempted to determine the immediate and lifetime direct costs of HIV disease from the costs associated with various clinically determined stages such as AIDS or CD4+ lymphocyte count." (PMID 21904673, 2012). "According to this definition, patients who present with less than 350 CD4 cells/mm3 or an AIDS-defining event and, thus, fail to derive maximal benefit from antiretroviral therapy are classified as late presenters." (PMID 23305650, 2012). "54/78 participants (69%) (re)started cART according to the CD4 count criteria, four patients (5%) because of severe symptoms/AIDS diagnosis, and 20 (26%) patients because of a preference by physician or patient to restart cART." (PMID 22479156, 2012). "As known, HIV/AIDS positive people have immunosuppression because of a decreased CD4+ T cell population including both naïve and memory T cells due to viral infection." (PMID 23243435, 2012). "A time updated Kaplan Meier plot illustrates the relatively low probability of AIDS event-free survival—roughly 70% after 10 y of suppression—should a patient's CD4 cell count remain below 200 cells/μl while suppressed." (PMID 22448150, 2012). "HIV infection usually leads to a progressive decline in number and functionality of CD4+ T lymphocytes, resulting in AIDS development." (PMID 22701517, 2012). "Enumeration of CD4 T lymphocyte plays a critical role in clinical management of HIV/AIDS patients for initiating and monitoring therapy." (PMID 22912668, 2012). "The measurement properties of the EQ-5D-5L holds potentials in monitoring changes in HRQOL, which are associated with meaningful clinical indicators, such as, CD4 thresholds, HIV/AIDS progression, or responses to ART treatment." (PMID 23116130, 2012). "Here the total CD4+ T cell counts decline from a value of 770 cells/μL at age 30 to a value below 200 cells/μL (AIDS) after approximately 10 years at age 40 in line with the clinical course of untreated HIV infection with R5 tropic virus." (PMID 22866173, 2012).
AIDS (continued). "Considering that functional and numerical normalization of CD4+ T-cells appears to be fundamental to prevent both AIDS-related and non-AIDS-related morbidity and mortality, there is a need of new therapeutic strategies for immunologic nonresponder patients." (PMID 22489250, 2012). "Following selection for X4 tropic virus after administration of maraviroc as monotherapy, total CD4+ T cell exhibit a rapid progression to AIDS within 1 year, so that AIDS occurs around the age of 33." (PMID 22866173, 2012). "It is well known that initially low and decreasing CD4+ cell counts during the year prior to cancer diagnosis are predictive of AIDS-defining malignancies (ADMs) such as Kaposi sarcoma and non-Hodgkin lymphoma as shown in the CASCADE study." (PMID 22474480, 2012). "In 2002, following the large proportion of people with antiretroviral therapy side effects/toxicity, the German AIDS Society recommended to start therapy below a threshold of 200 CD4+ cells per L." (PMID 22515400, 2012). "In contrast, the probability of AIDS event-free survival was roughly 95% after 10 y of suppression for patients maintaining a CD4 cell count of 500 cells/μl or more while suppressed." (PMID 22448150, 2012). "HIV-1 utilizes CD4 as the primary receptor for entry into cells; however, it is the viral co-receptor usage that greatly influences CD4 decline and progression to AIDS." (PMID 23202514, 2012). "We found lower naturally-acquired proliferative influenza-specific CD4+ T-cell responses in AIDS patients that was also present in asymptomatic HIV-infected adults with relatively high CD4 counts (>350 cells/μl)." (PMID 22715399, 2012). "A time-dependent covariates analysis showed that the significant factors for OS were HAART therapy, HIV score (based on performance status, prior AIDS diagnosis, and CD4+ count <100 cells/μL), and the IPI." (PMID 22400030, 2012). "The Gastrointestinal (GI) tract is critical to AIDS pathogenesis as it is the primary site for viral transmission and a major site of viral replication and CD4+ T cell destruction." (PMID 22511950, 2012). "Macaque K03135 developed AIDS with a CD4+ T-cell count consistently <200 cells/ul from 20 weeks post-inoculation onwards." (PMID 22427893, 2012). "It has been previously demonstrated how CD38+CD8+ phenotype has predictive value for progression to AIDS, even after adjustment for CD4+ levels, and it has been proposed as surrogate marker to clinical monitoring of HIV infection." (PMID 22110905, 2012). "Higher HIV RNA level prior to HAART predicted increased mortality even after adjusting for CD4+ count and prior clinical AIDS." (PMID 22339893, 2012). "Concerning the immune cell dynamics, it should display the decrease of the CD4+ T-cell count in the early acute phase, its slight replenishment to a constant level in the asymptomatic phase and its decrease during the AIDS phase." (PMID 23202449, 2012). "Recent research has added more credit to the macaque AIDS model, showing that, similarly to humans, rhesus macaques (Macaca mulatta) harbour a central memory CD4+ T-cell reservoir, which plays a pivotal role in AIDS pathogenesis." (PMID 22737073, 2012). "These complex mechanisms of CD4+ and CD8+ T cell death induced by HIV-1 infected macrophages will undoubtedly contribute to the total loss of T cells and finally AIDS development." (PMID 23035819, 2012). "This sample was from a 35 year old male with AIDS and Kaposi sarcoma, CD4+ T cell counts of 84/μl and a plasma HIV viral load of 124,000 copies/ml, who presented with left sided ataxia and weakness." (PMID 22536439, 2012). "HIV infection is characterized by an important decrease on CD4 T cell count, resulting in weakened immune responses that lead to AIDS-defining events." (PMID 22312424, 2012).
AIDS (continued). "Secondly, focusing on the established risk cutoff for developing opportunistic infections, all patients who present with a CD4+ T-cell count less than 200 cells/μL and/or an AIDS event should be considered to have “advanced HIV disease”." (PMID 22110905, 2012). "And, in a study which holds great significance for cancer patients, the stratification of these HIV patients according to their CD4 count demonstrates a clear link with the incidence of AIDS and non-AIDS-related malignancies." (PMID 22383042, 2012). "Based on the Joint United Nations Programme on HIV/AIDS estimate of approximately 19.8 million adults infected in sub-Saharan Africa, increasing the CD4 threshold would add between 4 and 5 million to the 10 million people currently still in need of treatment." (PMID 22802738, 2012). "Of 21 A.baumannii colonised/infected HIV-positive persons those with clinical AIDS (CD4<200 cells/mm3) had significantly higher in-ICU mortality and were more likely to have a positive blood culture." (PMID 23300673, 2012). "The study population was young (median age 34 years [IQR 28–40 years]) and had advanced HIV/AIDS (median CD4+ T-lymphocyte count 60 cells/μl [IQR 22–200 cells/μl])." (PMID 22745833, 2012). "Second, these findings suggest that patients with sustained viral suppression but low CD4 cell counts should be monitored regularly to ensure that any life-threatening AIDS-defining events are dealt with quickly and effectively." (PMID 22448150, 2012). "Admission CD4 count was available on ten patients who died from non-AIDS-defining malignancies, of whom 70% had a CD4 count greater than 200 cells/mm3." (PMID 22666562, 2012). "To test these predictions, we examined the effects of HAART initiated in the acute/early, pre-symptomatic and AIDS stages of infection on LT structure, naïve T cell apoptosis and restoration of naïve CD4+ T cell populations." (PMID 22241988, 2012). "T cell activation levels, viral load and CD4+ T cell counts at early stages of HIV-1 infection are predictive of the rate of progression towards AIDS." (PMID 23056251, 2012). "The rate of progression to a first new AIDS event or death decreased over time in all CD4 strata, except where patients had a low CD4 cell count (0 to <200 CD4 cells/μl)." (PMID 22448150, 2012). "Our model results in progression to AIDS within 1–1.5 years following emergence of X4-tropic virus in line with clinical observations for the case that X4 virus emerges when CD4+ T cell counts exhibit a value of approximately 400 cells/μL." (PMID 22866173, 2012). "This can occur through several pathways and contribute to the overall CD4+ T-cell depletion in HIV/AIDS patients." (PMID 22971934, 2012). "HIV-1 infection leads to necrotic/lytic cell death of the infected CD4+ T-cell, resulting in CD4+ T-cell depletion, a hallmark of HIV/AIDS." (PMID 22971934, 2012). "These outcome were achieved, despite that median VL was lower and mean baseline CD4 counts for non- AIDS patients on Atripla were higher than for those on other regimens." (PMID 23118869, 2012). "There was a strikingly variable positive effect of HAART on the γδ IEL counts in the AIDS patients, although immune reconstitution was usually confirmed by favourable CD4-cell counts and plasma HIV RNA levels in peripheral blood." (PMID 22238587, 2012). "The World Health Organization’s Clinical Staging System for HIV/AIDS was revised in 2005 and has a sensitivity of 51–52% and specificity of 68–88% in predicting CD4 count of <200 cells/mm3." (PMID 22296187, 2012). "A Cox proportional hazards model for time to a first new AIDS event or death also showed a gradient that depends on CD4 cell count." (PMID 22448150, 2012). "Guo and Carlin (2004) compared several link functions in their joint models, and showed that linking intercept (initial CD4 level) and the rate of CD4 decrease (slope) to survival provided a better fit in their analysis of data from AIDS clinical trials." (PMID 22773919, 2012).
AIDS (continued). "There is no doubt, however, that a Cryptosporidium infection increases the mortality rates in AIDS patients when comparing infected and uninfected AIDS patients with the same low CD4+count." (PMID 22685452, 2012). "The majority of patients (n = 63) were sampled at autopsy with late-stage AIDS and low CD4 counts (median CD4 T cell count was 87 cells/μL); however, this dataset also included 15 patients with pre-symptomatic HIV infection who died of non-AIDS related causes." (PMID 23166702, 2012). "More recently, poor DTH responses have been associated with increased risk of AIDS or death in women receiving HAART, and with reduced CD4 cell count reconstitution after HAART initiation." (PMID 22457767, 2012). "AIDS diagnosis and CD4 cell counts point out HIV progression and, therefore, they should always be adjusted for in the survival analysis if available." (PMID 24575328, 2012). "Feline immunodeficiency virus (FIV), the lentivirus of domestic cats responsible for feline AIDS, establishes a latent infection in peripheral blood CD4+ T-cells approximately eight months after experimental inoculation." (PMID 22754653, 2012). "CD4 testing is the recognized gold standard used to stage HIV/AIDS, guide treatment decisions for HIV-infected persons and evaluate effectiveness of therapy." (PMID 22676809, 2012). "Of note, the patient with diffuse FA changes was immunocompetent, whereas the other patients had acquired immunodeficiency disease syndrome (AIDS) and CD4 counts less than 100 cells/mm3." (PMID 22311604, 2012). "Patients receiving cART had lower nadir CD4 cell counts and more often experienced an AIDS-defining illness." (PMID 22883485, 2012). "Among the HIV positive women only, those with lower CD4 counts were more likely to report a prior stage IV WHO AIDS-defining condition (p<0.001)." (PMID 22532840, 2012). "The introduction of HAART as a modality of treatment in HIV positives has resulted in a dramatic decrease in AIDS-related morbidity and mortality and a great improvement in CD4 count of patients." (PMID 23056931, 2012). "The development of signs and symptoms of AIDS typically parallels laboratory testing for CD4 lymphocytes." (PMID 23077699, 2012). "Although more than 75% of patients with HIV-2 have asymptomatic prognoses throughout their lifetimes, all 3 of the CRF01_AB patients were found to be at an advanced stage of AIDS with low CD4+ cell counts and high HIV-2 VLs." (PMID 23094081, 2012). "This study shows that even though new AIDS events and death are uncommon in patients on cART with a suppressed viral load, these patients still benefit from a higher CD4 cell count." (PMID 22448150, 2012). "In this study, we compared two measures of late HIV diagnosis, one based on time between HIV and AIDS, the other based on initial CD4+ results." (PMID 22162804, 2012). "Those who present with less than 200 CD4 cells/mm3 or an AIDS-defining event are classified as patients with advanced HIV disease and are at increased risk of death." (PMID 23305650, 2012). "As expected by the severity of cryptosporidiosis in AIDS patients with low CD4+ counts[e.g.54], recent mouse and human studies have confirmed that cell-mediated immune responses play a crucial role in protection against cryptosporidiosis." (PMID 22685452, 2012). "Rates for first event of clinical AIDS or death per 100 person-years of follow-up by hepatitis B vaccine response for CD4 cell count, viral load, delayed-typy hypersensitivity response, and highly active antiretroviral therapy subgroups." (PMID 22457767, 2012). "Disease progression was defined as the time between HIV-1 infection and diagnosis of AIDS or when CD4 counts dropped below 200 cells/μl." (PMID 22412885, 2012). "It has also been suggested that a switch from R5 tropic to X4 tropic virus precedes the rapid CD4 decline and AIDS development in many cases." (PMID 23202514, 2012).
AIDS (continued). "At baseline, the patients in the two groups were similar with the exception of HIV medication regimens, CD4 count and presence of AIDS-defining malignancy." (PMID 21414215, 2011). "Reflecting their dramatic decrease in CD4+ counts (mean: 11/mm3), AIDS patients diagnosed with NTM (MOTT) disease were completely unreactive to all antigens tested (PPD: 147 ± 41; Ag85: 105 ± 32; PWM 104 ± 31) (resp)." (PMID 20936150, 2011). "Initiating HAART in patients with higher CD4 cell count levels is likely to reduce treatment expenses for ADEs and OIs in patients with AIDS." (PMID 21241494, 2011). "Median CD4 count in patients with any HIV-related admission (not only AIDS) was lower compared with patients admitted for reasons unrelated to HIV infection (100 versus 242 cells/mL, P < 0.001)." (PMID 22121360, 2011). "In a recent study conducted in France, six-month mortality among patients who initiated care with advanced HIV disease, defined as CD4 count <200/mm3 and/or AIDS, was 13.6 higher than among patients who initiated care early." (PMID 21226905, 2011). "SPVL is widely used as a prognostic indicator for AIDS, as individuals with a higher SPVL have a higher rate of CD4+ cell decline, and they tend to progress more rapidly to AIDS and die sooner as a consequence." (PMID 22022243, 2011). "The identification of GBV-C genotype 7 and its predominance among IDUs enhanced our curiosity: if there is a correlation between GBV-C genotypes and the presence of clinical AIDS markers, which include CD4+ cell count and HIV-1 viral load." (PMID 21998624, 2011). "Of the 2,938 newly diagnosed HIV-infected individuals, 2,507 (85,3%) had either a CD4 cell count or an AIDS diagnosis available." (PMID 21729332, 2011). "In this analysis we focused on patients with advanced HIV diagnosis and showed that 31.3% of patients initiated care at CD4 counts <200/mm3 or clinically-defined AIDS." (PMID 21226905, 2011). "Evaluation of the WHO HIV/AIDS staging guidelines in comparison to the newer CD4 cell count cut-offs for ART eligibility is needed to determine the potential level of misclassification." (PMID 21589912, 2011). "Late presentation was defined for individuals with a CD4 count below 350 cells/ml upon HIV diagnosis or diagnosis of AIDS within 3 months of HIV diagnosis." (PMID 21729332, 2011). "During 2008, 40% of AIDS patients (defined by CD4+ cell count less than 200 cells per microliter or WHO stage 4) were estimated to be on HAART in South Africa." (PMID 22140487, 2011). "Severe histoplasmosis is known to be among the AIDS-defining opportunistic infections affecting patients with very low CD4 cell counts in histoplasmosis-endemic areas." (PMID 21843324, 2011). "Of 752 patients, 76% were men, 60% were injection drug users (IDU), 59% had a history of an AIDS-defining illness, and 53% were coinfected with hepatitis C. The median baseline CD4 cell count was 141 cells/mm3." (PMID 21490781, 2011). "AIDS patients with CD4 counts less than 50 per cubic millimeter were more likely to have biliary symptoms and an increased risk of death at one year." (PMID 21994858, 2011). "The numbers of patients who presented to care with AIDS or CD4 counts <50/mm3, and <350/mm3 were 323 (17.6%), and 957(52.3%)." (PMID 21226905, 2011). "The CD4 lymphocyte count, currently regarded as the best prognostic marker for the development of AIDS, is a major criterion to decide on initiation of antiretroviral therapy." (PMID 21494630, 2011). "Nevertheless the utility of immune activation as a marker for CD4 decline and progression to AIDS under WT infection is validated here." (PMID 21255440, 2011). "The ACS+: HIV+ group were less immunocompromised as evidenced by higher CD4 counts (p = 0.013) and less patients with AIDS defining criteria (p = 0.01) which were all based on a CD4 count < 200 cells/ml3." (PMID 21970576, 2011).